APOE (apolipoprotein E)
Diseases named in the same sentence as APOE in open-access papers (continued):
Sharing a sentence is not in itself a finding about the gene and the disease.
atherosclerosis (continued). "To follow atherosclerotic plaque development by proteomics, we fed 8 week old atherosclerosis prone ApoE−/− mice for 8 and 16 weeks with a high-fat, western-type diet resulting in consistent formation of atherosclerotic lesions." (PMID 29208753, 2018). "Atherosclerosis-prone ApoE-/- mice were treated with intraperitoneal injections of MAGL-inhibitor JZL184 in order to investigate the impact of raised 2-AG levels on atherogenesis in vivo." (PMID 29813086, 2018). "We showed the normalisation of TC level due to EEP supplementation in our research on C57BL6 ApoE-knockout mice, which are a standard experimental model of atherosclerosis." (PMID 29614743, 2018). "For example, inhibiting farnesylation using manumycin A prevented the development of atherosclerosis in the aortic sinus of ApoE-null mice in vivo." (PMID 29689070, 2018). "In our previous study, DKO mice fed with WD developed 10-fold less atherosclerosis than their ApoE KO littermates." (PMID 29191818, 2018). "A study demonstrated that in apolipoprotein E-deficient (apoE−/−) mice, levels of TNF-α expression are closely associated with lesions in atherosclerosis-prone sites." (PMID 30524759, 2018). "As atherosclerosis is provoked by both inflammation and hyperlipidemia, we aimed to determine the effect of inulin supplementation on atherosclerosis development in hypercholesterolemic APOE*3-Leiden (E3L) mice." (PMID 29401645, 2018). "HCMV seropositivity is linked to a higher rate of mortality from atherosclerosis, and infection with MCMV increases the severity of atherosclerosis in the apoE−/− murine model of the disease." (PMID 30127279, 2018). "STAT4 deficiency reduces development of atherosclerosis and PVAT inflammation in apolipoprotein E (ApoE)−/− mouse and in insulin-resistant obese Zucker rats." (PMID 28891325, 2018). "In contrary, het mice with reduced Cyp27a1 expression had much more atherosclerosis than ApoE KO mice." (PMID 29191818, 2018). "Since ApoE−/− are prone to develop hyperlipidemia and atherosclerosis spontaneously as they age, it is possible that this propensity underlies the difference." (PMID 30483256, 2018). "Breeding Apoeh/h mice with mice deficient in LDL receptor gene expression led to new opportunities to study the process of apoE in atherosclerosis progression and its regression." (PMID 29789495, 2018). "A decreased expression of ANGPTL3 in apolipoprotein E (apoE)-null mice is protective in the development of atherosclerosis." (PMID 30011918, 2018). "The role of FGF21 in atherosclerosis was studied by evaluating its function in apolipoprotein E double knockout (apoE−/−) mice." (PMID 30157856, 2018). "This study intends to explore the molecular mechanism of BSKS against atherosclerosis in ApoE−/− mice." (PMID 29619063, 2018). "The present study demonstrated that exposure to high-dose CS induced atherosclerosis through the upregulation of miR-155 in aortas of ApoE KO mice." (PMID 29642385, 2018). "Conditional Apoe gene expression in HypoE mice and its derivatives thus represents a valuable tool to model the impact of hyperlipidemia in atherosclerosis cardiovascular disease and to study the contribution of apoE in these disorders." (PMID 29789495, 2018). "Advanced atherosclerotic lesions can be reduced in size and stabilized by IFN-γ inhibition, while administration IFN-γ accelerates atherosclerosis in ApoE−/− mice." (PMID 29760701, 2018). "In this research, apolipoprotein E−/− (apoE−/−) mice were used as an animal model of atherosclerosis to investigate the correlation of miR-217 with the IMT of ascending aorta and its role in inflammation and lipid metabolism process." (PMID 30041636, 2018).
atherosclerosis (continued). "The ApoE-knockout (ApoE–/–) mice can spontaneously develop hypercholesterolemia and atherosclerosis on a chow diet and have become a classic animal model for atherogenic hypercholesterolemia." (PMID 30443213, 2018). "In the same line, a recent study with apoE−/− mice showed that the development of atherosclerosis by microbiota was dietary dependent." (PMID 30347638, 2018). "Vascular dysfunction and atherosclerosis occur early in ApoE KO mice, which leads to reduced cerebral blood flow and dysfunctional autonomic regulation of the cerebrovasculature." (PMID 29510495, 2018). "This is a relative short time frame for atherosclerosis development, even in the ApoE KO model with WD." (PMID 29191818, 2018). "FGF21 deficiency in ApoE KO mice results in severe atherogenic phenotypes, but administering FGF21 to these ApoE KO mice ameliorates atherosclerosis." (PMID 29738435, 2018). "Future studies will be required to address the relevance of this and other protective mechanisms through which apoE can control atherosclerosis in humans including in an isoform-specific manner." (PMID 29789495, 2018). "In another study involving atherosclerosis-prone apolipoprotein E-null (Apoe−/−) mice, contradictory outcomes were observed." (PMID 29850631, 2018). "Among its other functions, apoE is involved in cholesterol efflux, especially from cholesterol-loaded macrophage foam cells and other atherosclerosis-relevant cells, and in reverse cholesterol transport." (PMID 30404132, 2018). "Here the data showed that atherosclerosis in ApoE−/− mice receiving MCC950 is reduced after 4 weeks of lesional development compared with controls." (PMID 29997514, 2018). "We compared the extent of atherosclerosis in this model with that seen in the most frequently utilized ApoE−/− mouse strain." (PMID 29770337, 2018). "ApoE−/− mice are widely used as animal models of atherosclerosis; however, the lipoprotein metabolism of this mouse strain is different from that in humans with hypercholesterolemia." (PMID 29770337, 2018). "Using in vitro adhesion assays and single SFK knockout mice crossed with the ApoE−/− model of atherosclerosis, we find that SFK signalling regulates platelet‐dependent recruitment of monocytes." (PMID 29974666, 2018). "We induced atherosclerosis in ApoE−/− mice by placing a tapered cast around the right common carotid artery (RCCA)." (PMID 30228313, 2018). "As a well-known atherosclerotic animal model, ApoE−/− mice developed foam cell-rich depositions in their aortas by the age of 3 months and ultimately developed atherosclerotic lesions similar to human atherosclerosis." (PMID 30402125, 2018). "Further, the amount of uptake of 111In-DANBIRT will characterize the degree of inflammation inside the vascular atherosclerotic plaque of apoE-deficient mice fed a HFD, known to demonstrate rapid progression of high-degree atherosclerosis." (PMID 30538613, 2018). "The results showed that DXXK treatment alleviated hyperlipidemia, fat accumulation, and atherosclerosis formation in ApoE–/– mice." (PMID 30443213, 2018). "Several studies have shown that the pharmacological targeting of SPT through the inhibition with myriocin protects from atherosclerosis in ApoE knockout mice." (PMID 30227643, 2018). "FGF21 protects against apoptosis in HUVECs by suppressing the expression of Fas; furthermore, FGF21 alleviated atherosclerosis by ameliorating Fas-mediated apoptosis in apoE−/− mice." (PMID 30157856, 2018).
atherosclerosis (continued). "Further studies, such as knocking down Cyp3a11 in ApoE KO and het mice would largely contribute to the clarification of the role of Cyp27a1 and Cyp3a11 in atherosclerosis development." (PMID 29191818, 2018). "Sitagliptin treatment primed monocyte differentiation towards the regenerative M2 subtype instead of the inflammatory M1 subtype and led to a reduced atherosclerosis progression (chronic vascular injury) in ApoE knockout mice." (PMID 29531541, 2018). "Studies in the atherosclerosis model apolipoprotein E (ApoE) knockout mice have shown that exposure to PM results in elevated levels of oxidized low-density lipoproteins, lipid peroxidation, and systemic oxidative stress." (PMID 30505291, 2018). "Since the prebiotic inulin is thought to beneficially affect gut microbiota, we aimed to determine the effect of inulin supplementation on atherosclerosis development in APOE*3-Leiden.CETP (E3L.CETP) mice." (PMID 30409998, 2018). "For this study apolipoprotein E null (ApoE−/−) mice were exposed to SHS to facilitate study in a COPD/atherosclerosis comorbidity model." (PMID 29364178, 2018). "Genetic variations in the APOE gene coding for apolipoprotein E constitute important risk factors both for AMD and atherosclerosis." (PMID 30519244, 2018). "Taken together, these results show that FGF21 alleviated the progression of atherosclerosis by suppressing Fas-mediated apoptosis in apoE−/− mice." (PMID 30157856, 2018). "Based on our observations in DKO mice and to investigate the relevance of CYP3A11 for cholesterol homeostasis, we analyzed the effect of Cyp3a11 induction by RIF on atherosclerosis in ApoE KO and het mice with reduced Cyp27a1 expression." (PMID 29191818, 2018). "To dissect the role of nicotine during the progression of atherosclerosis, we performed HE and Oil Red O staining in histological sections of the aortic sinus of the ApoE−/− mice." (PMID 29416034, 2018). "Atherosclerosis-prone ApoE−/− mice fed a butyrate-supplemented chow diet are protected from atherosclerosis, and mounting evidence shows that butyrate blunts macrophage inflammation, suggesting that butyrate has anti-atherogenic properties." (PMID 30282904, 2018). "In ApoE−/− mice, overexpression of Nox4 in endothelial cells reduced atherosclerosis, mainly in the abdominal section of the descending aorta, in animals fed a Western diet for 24 weeks." (PMID 29710840, 2018). "At 10 weeks of age, ApoE−/− mice were started on a western diet to induce hyperlipidemia and accelerate the development of atherosclerosis." (PMID 29618740, 2018). "Consistent with the modulation of macrophage activation, it has been reported that HDL induced atherosclerosis regression and altered the inflammatory properties of plaque monocyte-derived cells in apoE-knockout mice." (PMID 30558209, 2018). "The expression of apoE in the macrophage has long been recognized to suppress atherosclerosis by preventing foam cell formation in the vessel wall." (PMID 29789495, 2018). "ROS and DNA damage data suggest that the increased apoptosis of monocytes that we observed in apoE−/− animals, contribute to the progression of atherosclerosis." (PMID 30185234, 2018). "The pharmacological inhibition of glucosylceramide synthase that is responsible for the synthesis of glucosylceramides has been reported to ameliorate atherosclerosis in ApoE knockout mice and rabbits." (PMID 30227643, 2018). "To assess the anti‐inflammatory effects of AVE0991 during the early stages of atherosclerosis, we focused on characterization of vascular and perivascular immune cells between the 16th and the 24th week of age in chow‐fed ApoE‐/‐ mice." (PMID 27935022, 2017). "In order to investigate the contribution of Cd39 in atherosclerosis, we crossed ApoE KO to Cd39 KO C57BL6 mice generating DKO mice." (PMID 28487312, 2017).
atherosclerosis (continued). "The findings of this study demonstrate the ability of the proposed methods to non-invasively quantify the spatial variations in local PWV along the aorta of ApoE (−/−)-mice as a relevant model of atherosclerosis." (PMID 29037199, 2017). "Previous studies have demonstrated high titers of IgG antibodies directed against MDA-LDL in 5–6 month old atherosclerosis-prone ApoE-/- mice fed a diet of regular mouse chow." (PMID 28222187, 2017). "A significant loss of CD11c+ macrophages was evident in ApoE-/-Irf5-/- mice in the aorta, draining lymph nodes, and bone marrow cell cultures, indicating that IRF5 maintains CD11c+ macrophages in atherosclerosis." (PMID 28698173, 2017). "It has also been shown that A-FABP inhibitors protected against atherosclerosis in apoE-knockout mice." (PMID 28777310, 2017). "A subsequent set of experiments used the ApoE–/– mouse model to establish the impact of antibody blocking of TILRR function on progression of atherosclerosis." (PMID 28920098, 2017). "Apolipoprotein E: structure determines function, from atherosclerosis to Alzheimer’s disease to AIDS." (PMID 29204218, 2017). "The DKO Cd39−/−/ApoE−/− mice studied here have significantly delayed progression of atherosclerosis." (PMID 28487312, 2017). "Lentivirus carrying the let‐7g gene was injected to apolipoprotein E knockout (apoE−/−) mice to confirm let‐7g's effect on preventing atherosclerosis." (PMID 28699690, 2017). "In this study, the ABCC1 inhibitor MK571 significantly improved endothelial dysfunction and reduced atherosclerotic lesion formation in the apolipoprotein E (ApoE) knockout mouse model of atherosclerosis." (PMID 28383515, 2017). "The role of this potential auto-reactive antigen in atherosclerosis was tested using immunization as a strategy to manipulate the auto-immune response in ApoE(-/-) mice." (PMID 29091929, 2017). "In fact, CD4+ T cells increase the progression of atherosclerosis in Apolipoprotein E (ApoE) knockout mice." (PMID 28241014, 2017). "In apolipoprotein E (ApoE)-deficient mice, an atherosclerotic animal model, inhibition of TSP1 and TSP4 caused delayed atherosclerosis progression and less inflammatory conditions." (PMID 28714932, 2017). "The present study provides the first demonstration that orally administered CrP impedes development of atherosclerotic lesions in STZ-induced hyperglycemic ApoE−/− mice, a mouse model of combined atherosclerosis and type 1 diabetes." (PMID 28345659, 2017). "OPG, a protein that inhibits vascular calcification, was shown to reduce atherosclerosis in apoE knockout mice." (PMID 29023576, 2017). "The current study was designed to investigate the influence of prolonged treatment with agmatine on the development of atherosclerosis and changes in lipid profile in apoE-/- mice using morphological, biochemical, and molecular methods." (PMID 28777310, 2017). "Mice with double knockout of ApoE and POLG accumulate mitochondrial DNA damage, which promoted atherosclerosis and was associated with the formation of vulnerable plaques." (PMID 28095860, 2017). "Mice with both CSE and apoE gene knockout had more extensive atherosclerosis burden than those with either apoE or CSE knockout." (PMID 29066981, 2017). "In ApoE-/- mice fed a high fat diet, Icariin reduces atherosclerosis by reducing the concentrations of TC and TG." (PMID 29075193, 2017). "In the present study, we explored the effects of GTP, mainly consisting of EGCG and catechin, on atherosclerotic lesions and lipid metabolism in ApoE-knockout mice (an animal model of atherosclerosis)." (PMID 28777810, 2017). "Effect of different flavonoids on atherosclerosis lesion area in ApoE-/- mice and key aspects of the methods of the included studies." (PMID 28742839, 2017).
atherosclerosis (continued). "Microbiota can also protect from atherosclerosis, as recently shown when Akkermansia municiphila reversed Western diet-induced atherosclerosis and endotoxemia in ApoE-knockout mice." (PMID 28609252, 2017). "In ApoE-/- mice, vessel wall thickness increased from 8 weeks to 32 weeks of age, consistent with the age-dependent worsening of atherosclerosis in ApoE-/- model." (PMID 28982198, 2017). "Using the descending aorta of chow‐fed ApoE−/− mice, before significant atherosclerotic plaque develops, we gained insight into the early events in atherosclerosis." (PMID 27935022, 2017). "The aim of this study was to determine the effect of polyphenol-rich ethanol extract of bee pollen (EEP) on atherosclerosis induced by a high-fat diet in ApoE-knockout mice." (PMID 29258230, 2017). "In this study, we investigated mechanisms of QSYQ on the immune system and distinct cytokines involved in atherosclerosis using ApoE-/- mice." (PMID 29137256, 2017). "It has been shown that the injection of activated platelets in ApoE KO mice promotes leukocyte binding to endothelium and higher inflammation leading to exacerbation of atherosclerosis." (PMID 28487312, 2017). "Using the descending aorta of chow‐fed ApoE−/− mice, before significant atherosclerotic plaque develops, we gained insight to early events in atherosclerosis." (PMID 27935022, 2017). "Transgenic and knockout mouse strains including those which demonstrate accelerated atherosclerosis (ApoE-/-), simulate obesity/diabetes (db/db), or altered eNOS expression, have immediate relevance to a more comprehensive evaluation of new graft materials." (PMID 28355300, 2017). "In the present study, we also demonstrated a significant increase in IgG and IgM antibodies against M2FA in the atherosclerosis-prone ApoE−/− mice." (PMID 28883613, 2017). "Our research verified that Tan IIA significantly exerted an inhibitory effect on the initiation and progression of atherosclerosis in ApoE–/– mice through suppressing the expression of adhesion molecules and inflammatory cytokines secretion in serum." (PMID 28412716, 2017). "Our data demonstrated that folic acid ameliorated atherosclerosis in ApoE−/− mice and also altered the abundance of MCP1 and VEGF expression." (PMID 28475147, 2017). "Similarly, ApoE deficiency in mice (ApoE-/-) leads to hyperlipidaemia and spontaneous development of atherosclerotic lesions from the age of 10 weeks, designating the ApoE-/- mouse model as one of the best established experimental tools to study atherosclerosis." (PMID 28688452, 2017). "We investigated the effect of exogenous agmatine on the development of atherosclerosis and changes in lipid profile in apolipoprotein E knockout (apoE-/-) mice." (PMID 28777310, 2017). "In this study, we showed that rebamipide reduces the development of atherosclerosis by controlling the balance between Th17 and Treg cells in western-dieted ApoE-KO mice." (PMID 28241014, 2017). "Several inhibitors have been developed in an attempt to reduce atherosclerosis, with Nox2ds-tat recently showing that treatment of ApoE-/- with this peptide reduced lesion size in the aorta and carotid arteries." (PMID 28688452, 2017). "The effect of gugulipid (1 mg/g of atherogenic diet by 12 weeks) on blood cholesterol level and progression of atherosclerosis was evaluated in atherogenic diet-fed male ApoE KO mice." (PMID 28910310, 2017). "As compared with the C57BL/6 normal control, HFD-fed apoE-/- mice displayed multiple atherosclerotic lesions in the aorta arch, revealing remarkable atherosclerosis." (PMID 29212261, 2017).